TRPV1 (transient receptor potential cation channel subfamily V member 1)
Diseases named in the same sentence as TRPV1 in open-access papers (continued):
Sharing a sentence is not in itself a finding about the gene and the disease.
migraine (continued). "As TRPV1 gene polymorphism determines sensitivity to capsaicin further studies are needed to explore the role of genotyping-based approaches in migraine patients." (PMID 29915934, 2018). "Further evidence about functional associations of TRPV1 gene variants has been raised in Spanish Caucasian migraine patients in whom the presence of the TRPV1 rs222741 variant conferred a disease risk." (PMID 28658281, 2017). "The capsaicin and heat responsive ion channel TRPV1 is expressed on trigeminal nociceptive neurons and has been implicated in the pathophysiology of migraine attacks." (PMID 26109436, 2015). "Polymorphisms in the TRPV1 gene are associated with increased pain sensitivity and response to botulinum toxin therapy, highlighting its significance in the inflammatory and nociceptive processes in migraines." (PMID 40002876, 2025). "Notably, a recent study published by Yakubova and colleagues in 2021 reported a statistically different distribution of TRPV1 rs8065080 genotypes between EM and CM, suggesting a possible role of rs8065080 as a risk factor for migraine chronification." (PMID 39105976, 2025). "Transient receptor potential vanilloid subfamily member 1 (TRPV1) expressed on trigeminal nerve injury receptors has been proven to play a key role in both migraine and asthma.TRPV1 releases neuropeptides, causing neurogenic inflammation, leading to vasodilation, and triggering migraine." (PMID 38650934, 2024). "ROS and CGRP, TRPA1, and TRPV1 can interact to cause migraine." (PMID 37123270, 2023). "Homozygous allelic variant rs222747 in TrpV1 was associated with higher glutamate activation, which in turn may be translated into increased cortical excitability in migraine sufferers." (PMID 37291550, 2023). "At the same time, acute or chronic (nitroglycerine-induced migraine rat model) NO administration increased the pro-nociceptive effects of capsaicin, which may be associated with S-nitrosylation of TRPV1 or other targets impacting capsaicin-evoked firing." (PMID 37108677, 2023). "Genetic studies suggest that the TRPV1 gene is linked to migraines." (PMID 36614146, 2022). "Here was evaluated the frequency distribution of AA, AG and GG variants of 1911A>G in the TRPV1 gene in healthy individuals and patients with episodic (EM) and chronic migraine (CM) to test the influence of the SNP on susceptibility to these forms of migraine." (PMID 34794375, 2021). "This could explain why women exhibit a higher susceptibility to migraine, and suggests that potential interaction of TRPV1 and ANO1 in TG neurons may be involved in migraine initiation." (PMID 31336748, 2019). "Moreover, the co-activation of Piezo1 and TRPV1 nociceptive channels after stroke raises the interesting issue of potential functional interactions between these two signaling pathways, likely implicated in migraines." (PMID 36293444, 2022). "In addition, migraine hyperalgesia is associated with reduced TRPV1 activation threshold." (PMID 26043006, 2015). "The relationship between dysregulated insulin metabolism and migraine involves several interconnected pathways: TRPV1 sensitization and CGRP release, mitochondrial dysfunction with oxidative stress, and systemic and neurogenic inflammation." (PMID 40426647, 2025). "TRPV1 also plays an important role in migraine pathogenesis, and a recent study confirms that TRPV1 is upregulated in TNC of the nitroglycerin‐induced migraine rat model." (PMID 41399206, 2025). "Amounts of studies on the effect of CGRP and TRPV1 in migraine have made them as therapeutic targets for migraine treatment and prevention." (PMID 39965247, 2025). "The expression and colocalization of TRPM8 and TRPV1 in TG neurons are increased in a meningeal inflammation‐based migraine model." (PMID 41399206, 2025). "In particular, activated TRPA1, TRPM2, TRPM8, and TRPV1 channels participate in migraine progress through amplifying neuroinflammation." (PMID 41399206, 2025).
migraine (continued). "Hyperinsulinism contributes to migraine through TRPV1 sensitization, increased CGRP release, oxidative stress, mitochondrial dysfunction, and systemic inflammation." (PMID 40426647, 2025). "As a word of caution, small-molecule TRPV1 antagonists were effective analgesic agents in animal models of inflammatory and neuropathic pain, yet, they failed in clinical trials to relieve migraine or osteoarthritis pain." (PMID 38339399, 2024). "These conditions include fibromyalgia, irritable bowel syndrome, temporomandibular disorder, rheumatoid arthritis, osteoarthritis, and migraines, all of which are associated with TRPV1 upregulation." (PMID 39125611, 2024). "Several studies have reported the overexpression of TRPV1 in certain diseases such as rheumatoid arthritis, neuropathic pain, bone cancer, fibromyalgia, migraine, and irritable bowel syndrome." (PMID 39125611, 2024). "The success of BoNT/A and its interactions with TRPV1 provide support for targeting TRP channels in migraine treatment." (PMID 37175602, 2023). "Associations between SLC17A8, TRPV1, TRPV4 and TRPM8 gene polymorphisms and anxiety and depression in migraine patients." (PMID 37303955, 2023). "Historically, it was TRPV1 and capsaicin that showed a potentially causative role of TRP channels in cluster headaches and migraine." (PMID 37326902, 2023). "Associations between SLC17A8, SHANK1, TRPV1, TRPV3 and TRPM8 gene polymorphisms and the risk of migraine by aura." (PMID 37303955, 2023). "TRPA1, along with transient receptor potential cation channel subfamily V member 1 (TRPV1), TRPV4, and transient receptor potential cation channel subfamily M member 8 (TRPM8), are most consistently reported to associate with migraine among all TRP channels." (PMID 37326902, 2023). "TRPV1 can be activated in the meninges during migraine attacks, and the expression of TRPV1 changes during CSD." (PMID 37108677, 2023). "Such physical interactions between two receptors can alter the receptor properties and excitability, so the cooperation of TRPA1 and TRPV1 should be carefully considered in chronic pain-related disease, such as in migraine, studies." (PMID 36982450, 2023). "Despite a suggestive role for TRPV1 in the migraine headache mechanism, the efficacy of TRPV1-antagonists in anti-migraine therapy is still uncertain." (PMID 36986537, 2023). "Out of the six TRP subfamilies, only TRP melastatin (eight members, TRPM1-8), TRP vanilloid (six members, TRPV1-6), and TRP ankyrin (one member, TRPA1) are associated with migraines." (PMID 36831105, 2023). "In recent decades, the classical TRP channel TRPV1, the mechanosensor Piezo channels, or the purinergic receptor PY have been identified as potential targets of certain migraine-triggering substances." (PMID 36982450, 2023). "The present study showed that TRPV1 rs8065080, TRPV3 rs7217270, and TRPM8 rs17862920 were significantly associated with migraine or MO risk." (PMID 37303955, 2023). "In recent years, an increasing number of studies have focused on discovering TRPV1 antagonists and agonists/desensitizers as therapeutic solutions for chronic, neuropathic and inflammatory pain, but also for migraine and cluster headache." (PMID 36559057, 2022). "In particular, the subtypes ankyrin 1 (TRPA1) and vanilloid 1 (TRPV1) are activated by migraine provoking agents." (PMID 35350752, 2022). "In another animal model of migraine, after application of inflammatory soup on the dura mater, the TRPV1 immunoreactivity is increased in the dorsal horn of the spinal cord, which was modulated by sumatriptan." (PMID 36614146, 2022). "Our recent research found that XMT extract has also displayed a decline in the expression of TRPV1 on the trigeminal ganglion neurons of migraine rats." (PMID 35350752, 2022). "In the nitroglycerin model of migraine, chronic intraperitoneal administration of ghrelin can reduce mechanical and thermal hypersensitivity and the associated increased CGRP and TRPV1 mRNA expression in the TG." (PMID 36614146, 2022).
migraine (continued). "Recent research found, in the trigeminal ganglion, TRP channels co-localize with CGRP, and the number of CGRP and TRPV1 immune reaction cells increase in the trigeminal ganglion of migraine rats." (PMID 35350752, 2022). "A growing number of studies have linked TRP channels with migraine, specifically TRPA1 and TRPV1 channels which are expressed in trigeminal sensory neurons." (PMID 34790097, 2021). "TRPV1 has been suggested to have an important role in dural vasodilation, which is one of the proposed basic mechanisms in migraine pathophysiology." (PMID 35002925, 2021). "In this study, to investigate some molecular alterations involved in migraine chronification, serum levels of TRPV1, VIP, and PACAP were evaluated in patients with episodic and CM, and also healthy individuals." (PMID 35002925, 2021). "Several SNPs in TRPV1, TRPV3, and TRPM8 were found to be associated with migraine susceptibility in meta-analyses of observational studies and GWAS." (PMID 33193064, 2020). "The first hint that TRPV1 is involved in migraine was demonstration of its co-expression with CGRP in rat TG neurons and mouse dural afferent neurons, suggesting a crucial role for TRPV1 in migraine." (PMID 31336748, 2019). "In the same manner, a recent study showed that migraine patients exhibit enhanced extracephalic capsaicin-induced pain sensation during interictal periods, supporting the contribution of TRPV1 to interictal sensitization." (PMID 31336748, 2019). "Another substantial link between migraine and TRPV1 was the demonstration that a frequent migraine trigger, ethanol, induced neurogenic vasodilation via TRPV1 activation and subsequent CGRP release in the TGVS of guinea pigs." (PMID 31336748, 2019). "Although TRPV1 antagonists failed in a prior human trial for migraine, there is still a clear role for TRPV1 in the activation of meningeal nociceptors and thus potential for alternate therapeutics to show efficacy." (PMID 30970581, 2019). "Data are being accumulated on the effect of sex hormones on TRP channels such as TRPV1 that make pivotal contributions to nociceptor excitability and sensitization in migraine and other chronic pain syndromes." (PMID 30155469, 2018). "The discovery of this novel binding site in the TRPV1 channel opens new avenues for the design of novel receptor antagonists for the treatment of migraine." (PMID 30155469, 2018). "We propose that activation of TRPV1 and TRPA1 receptors by H2S during neuro-inflammation conditions contributes to the nociceptive firing in primary afferents underlying migraine pain." (PMID 28798669, 2017). "We suggest that up-regulation of CSE or CBS during migraine related neuro-inflammation in meninges generates H2S resulting in activation of pro-nociceptive TRPV1 and TRPA1 receptors." (PMID 28798669, 2017). "Based on these basic and pre-clinical findings, a number of TRPV1 modulators have been investigated in clinical trials for migraine/headache conditions." (PMID 27854251, 2016). "TRPV1, a calcium permeable ion channel, is activated by heat and capsaicin, and is considered to play a major role in the pathogenesis of migraine." (PMID 27600145, 2016). "Accordingly, TRPV1 antagonists have been shown to be effective in alleviating migraine-like symptoms in rats." (PMID 27854251, 2016). "Additional clinical studies with other TRPV1 antagonists should therefore be conducted before definitive conclusions on the role of TRPV1 in migraine can be drawn." (PMID 26109436, 2015). "A recent study investigating single nucleotide polymorphisms among the Spanish population identified the TRPV1 and TRPV3 genes as likely candidates for contributing to an increased genetic susceptibility to migraine." (PMID 26109436, 2015). "The well-known migraine trigger ethanol has been shown to induce neurogenic vasodilation via a TRPV1-mediated release of CGRP." (PMID 26109436, 2015).
migraine (continued). "Capsaicin activates the heat and pH-sensitive ion channel Transient Receptor Potential Vanilloid 1 (TRPV1), which seems to be involved in the pathophysiology of migraine." (PMID 26109436, 2015). "In this study we applied two in vivo models of migraine to test the efficacy of two TRPV1 antagonists." (PMID 26109436, 2015). "Accordingly, the anti-migraine drug sumatriptan was recently shown to block trigeminal TRPV1 channels." (PMID 26109436, 2015). "Activation of TRPV1 causes release of CGRP from trigeminal nerve terminals and neurogenic inflammation within the meninges, possibly initiating migraine attacks." (PMID 26109436, 2015). "Another TRPV1 antagonist, A-993610, was recently shown to be ineffective in different animal models of migraine." (PMID 26109436, 2015). "Nevertheless, the use of TRPV1 antagonists for the treatment of acute headache or migraine is controversial." (PMID 26109436, 2015). "Consistent results were obtained for TRPV3 rs7217270 in the Migraine with aura group and TRPV1 rs222741 in the overall migraine group, suggesting the involvement of the vanilloid TRPV subfamily of receptors to the genetic susceptibility to migraine." (PMID 23815568, 2013). "A number of different receptors, such as calcitonin gene-related peptide (CGRP), TRPV1 and glutamate receptors, are currently being targeted by potential novel migraine therapeutics." (PMID 19917094, 2009). "Notably, while capsaicin and TRPV1 activation have been identified as potential triggers for migraines, they are also being explored as therapeutic targets for migraine treatment." (PMID 39965247, 2025). "Possible relief from migraine symptoms may be achieved through the inhibition of the NGF/TRPV1/COX-2 pathway by Shaoyao Gancao Decoction." (PMID 38836002, 2024). "In this regard, the potential role of TRPV1 in migraine has been recently reviewed." (PMID 39407099, 2024). "Since then, the focus of most TRPV1 drugs for migraine treatment has been on TRPV1 antagonists." (PMID 37175602, 2023). "Transient receptor potential vanilloid subfamily member 1 (TRPV1), expressed in the membranes of sensory afferent fibers and on the trigeminal nociceptors, has been shown to play a key role in the pathophysiology of both migraines and asthma." (PMID 37240671, 2023). "Thus, TRPV1 agonists and antagonists have been identified as potential therapeutic agents for migraine management." (PMID 37175602, 2023). "Extensive preclinical studies focusing on TRP ion channels have concluded that TRPA-1 and TRPV-1 could play crucial roles in the activation of several substances (as migraine triggers) that evoke migraine pain." (PMID 36835524, 2023). "Associations between the GRIK2, TRPV1, TRPV3 and TRPM8 gene polymorphisms and the risk of migraine." (PMID 37303955, 2023). "Furthermore, the anti-migraine drug sumatriptan was recently shown to block trigeminal TRPV1 channels." (PMID 37175602, 2023). "For instance, TRPA1 and TRPV1 might be involved in migraine, headache and dental pain, for which TMD shares significant co-morbidity." (PMID 37033371, 2023). "As the main members of the TRP family, the polymorphisms of TRPV1, TRPV4 and TRPM8 genes may play an important role in the occurrence and development of migraine." (PMID 37303955, 2023). "TRPV1 activity is further modulated by inflammatory mediators, such as prostaglandin E2 and bradykinin, which trigger the release of pro-inflammatory and pro-migraine neuropeptides, including CGRP and SP, within the meninges." (PMID 37175602, 2023). "XMT extract can significantly improved the behavioral performance of rats with migraine, and its mechanism of action might involve regulating the activity of TRPV1-CGRP/CGRP-R pathway." (PMID 35350752, 2022). "TRPV1 plays an important role in the pathophysiology of migraine." (PMID 36704329, 2022).
migraine (continued). "XMT extract could significantly improve the macroscopic performance and behavioral performance of migraine rats, its mechanism of action involves regulating the TRPV1-CGRP/CGRP-R pathway." (PMID 35350752, 2022). "In addition, we assessed the relative contribution of mechanosensitive TRPM3 channels and that of mechanosensitive Piezo1 channels and transient receptor potential vanilloid 1 (TRPV1) channels to nociceptive firing relevant to migraine in both sexes." (PMID 35012445, 2022). "Furthermore, increasing attention has been given to the capsaicin-gated channel transient receptor potential vanilloid subfamily member 1 (TRPV1), suggested to play a role in migraine as well as the sensitization phenomena related to it36." (PMID 35650312, 2022). "This indicates that the occurrence of migraine might be closely related to the expression of TRPV1-CGRP/CGRP-R pathway in trigeminal nerve." (PMID 35350752, 2022). "As the activation of these channels in meningeal afferents has previously been proposed to play a role in migraines, it is tempting to speculate that mechanisms converging on Piezo1 and TRPV1 channels play a role in various types of headaches." (PMID 36293444, 2022). "Trigeminal neurons that synapse at the caudal trigeminal nucleus express TRPV1, and TRPV1-mediated CGRP, a potent vasodilator, release has been implicated in migraine-type headaches, and cannabis has been shown to be effective in the treatment of migraines." (PMID 36077412, 2022). "Additionally, transient receptor potential vanilloid 1 (TRPV1), a Na+ and Ca2+ permeable channel, is among the other factors which are assumed to play a role in migraine pathogenesis." (PMID 35002925, 2021). "Therefore, the role of TRPV1 in the pathophysiology of migraine has attracted much attention in the recent years." (PMID 35002925, 2021). "In chronic migraine patients, intranasal capsaicin was able to mitigate the migraine pain and TRPV1 agonists might be effective most likely due to desensitization in the acute treatment of migraine as well." (PMID 33789568, 2021). "Therefore, considering the different results of previous studies, it seems that the role of these factors should be appraised while introducing TRPV1, VIP, and PACAP as risk biomarkers for migraine progression." (PMID 35002925, 2021). "Based on these data, it seems that serum levels of TRPV1 may have a role in migraine progression but more evaluations are needed." (PMID 35002925, 2021). "Ethanol has shown that may be able to induce migraines through TRPV1 stimulation followed by CGRP elevation in the trigeminovascular system." (PMID 35002925, 2021). "The authors concluded that TRPV1 may play a role in the pathophysiological mechanisms relevant to migraine." (PMID 31948011, 2020). "Ultimately, while there may be a role for this channel in meningeal afferent signaling and in headache, the TRPV1 antagonist SB-705498 failed in a clinical migraine study." (PMID 30970581, 2019). "Hence, although TRPV1 is currently recognized as a key player in migraine initiation, it is also likely involved in other phases and characteristics of migraine." (PMID 31336748, 2019). "Indeed, a number of TRPV1 antagonists have already entered phase 1 and 2 clinical trials for the indications of migraine, osteoarthritic pain, chronic cough, and atopic dermatitis, just to cite a few examples." (PMID 31344877, 2019). "More recent work from these authors has shown that repeated exposure to acrolein potentiates meningeal vasodilatory responses to TRPA1 and TRPV1 activation and leads to migraine-like cutaneous hypersensitivity and increased responses of the trigeminal afferent system to touch." (PMID 30970581, 2019). "TRPA1 and TRPV1 have also been involved in the development of migraine, which can be activated by a number of TRPA1 agonists and might be attenuated by repeated desensitizing administration of capsaicin to the nasal mucosa." (PMID 28649203, 2017).